CES1 (carboxylesterase 1)
Diseases named in the same sentence as CES1 in open-access papers (continued):
Sharing a sentence is not in itself a finding about the gene and the disease.
atherosclerosis (9 papers, 2016 to 2024). A disease characterized by the build-up of fatty material and calcium deposition in the arterial wall resulting in partial or complete occlusion of the arterial lumen. "The global loss of Ces1/Ces1g avoids the development of atherosclerosis by inhibiting intestinal cholesterol and triglyceride absorption." (PMID 35135573, 2022). "In conclusion, global loss of Ces1/Ces1g protects against the development of atherosclerosis by inhibiting intestinal cholesterol and triglyceride absorption and promoting macrophage cholesterol efflux." (PMID 29259301, 2017). "So far, it is unclear whether loss of mouse Ces1/Ces1g has any impact on atherosclerosis." (PMID 29259301, 2017). "Similar to loss of hepatic Ces3/Ces1d function, inactivation of hepatic Ces1/Ces1g in Apoe−/− mice aggravated the development of atherosclerosis." (PMID 29259301, 2017). "To understand how global inactivation of CES1 ameliorates atherosclerosis, we knocked down hepatic Ces1/Ces1g expression in Apoe−/− mice using an adenovirus expressing Ces1 shRNA (Ad-shCes1)." (PMID 29259301, 2017). "CES1 also hydrolyzes cholesteryl ester in lipid metabolism in human macrophages and hepatocytes, inferring that CES1 could be a potential drug target for the treatment of metabolic diseases, such as diabetes and atherosclerosis." (PMID 38399287, 2024). "Our data indicate that Ces1/Ces1g plays a critical role in the pathogenesis of atherosclerosis." (PMID 29259301, 2017). "In summary, we demonstrate that global inactivation of Ces1/Ces1g ameliorates the development of atherosclerosis by inhibiting intestinal cholesterol absorption, promoting macrophage cholesterol efflux and M2 macrophage polarization, and inducing bile acid production." (PMID 29259301, 2017). "So far, the role of mouse Ces1/Ces1g deficiency in atherosclerosis is not elucidated." (PMID 29259301, 2017).
hyperlipidemia (8 papers, 2012 to 2023). "Ablation of Ces1/Es-x expression results in postprandial hyperlipidemia due to increased secretion of chylomicrons." (PMID 23145182, 2012). "This strongly suggests the importance of the intestinal contribution to the characteristic hyperlipidemia in Ces1/Es-x−/− mice." (PMID 23145182, 2012). "However, other researches showed contradicting results, wherein Ces1/Es-x knockout mice resulted in increased hepatic lipogenesis and hyperlipidemia, accompanied by fat deposition in peripheral tissues." (PMID 35135573, 2022). "Interestingly, knockdown of hepatic Ces1/Ces1g in Apoe−/− mice resulted in hyperlipidemia and exacerbated Western diet-induced atherogenesis." (PMID 29259301, 2017). "Four representational genes, including Apolipoprotein B gene (APOB), Carboxylesterase 1 gene (CES1), Delta Like Non-Canonical Notch Ligand 1 gene (DLK1), Lipase Maturation Factor 1, (LMF1), were contributed to hyperlipidemia." (PMID 27888796, 2016).
prostate carcinoma (8 papers, 2020 to 2025). A carcinoma that arises from epithelial cells of the prostate gland. "Consistently, we found that rs8192935 and rs8192950 G alleles were associated with a decrease in the mRNA expression levels of CES1, and lower CES1 expression showed a poorer prognosis for prostate cancer patients." (PMID 32466188, 2020). "According to two prostate cancer studies from Taylor and TCGA, lower expression levels of CES1 were associated with prostate cancer, a higher Gleason score, a more advanced stage, and worse survival in patients." (PMID 32466188, 2020). "However, validation in a larger population and further functional studies are needed to identify the tumor suppressive role of CES1 underlying prostate cancer progression." (PMID 32466188, 2020). "The role of PXR in the homeostasis of androgens may provide clues to the mechanism underlying the observed association between CES1 and prostate cancer progression." (PMID 32466188, 2020). "In prostate cancer tissues compared with normal prostate tissue, the expression of CES1 was downregulated and high levels of CES1 expression were negatively correlated with tumor stage, metastasis, and Gleason score." (PMID 38033743, 2023). "In this same study, melatonin upregulated CES1 expression, which decreased lipid accumulation and cell activity by prostate cancer cells, as well as inhibited castrate-resistant prostate cancer progression, and reversed enzalutamide progression." (PMID 38033743, 2023). "In conclusion, our findings suggest that CES1 rs8192935 and rs8192950 are associated with BCR and that CES1 plays a tumor suppressive role in prostate cancer." (PMID 32466188, 2020). "Furthermore, functional studies revealed that these SNPs are in eQTL affecting the expression of CES1 and are subsequently correlated with tumor aggressiveness and prostate cancer prognosis." (PMID 32466188, 2020). "Finally, no direct biological experiments were conducted to investigate the exact mechanism of action of CES1 rs8192935 and rs8192950 on prostate cancer progression, which should be explored in the future." (PMID 32466188, 2020). "Therefore, further experimental characterization is required to elucidate the function of these SNPs/CES1 in prostate cancer." (PMID 32466188, 2020). "Our results suggest that rs8192935 and rs8192950 may reduce the expression of CES1, resulting in a poor prognosis, and could be potential biomarkers of clinical outcome in prostate cancer patients." (PMID 32466188, 2020). "We found that CES1 rs8192935 and rs8192950 might be a prognostic factor for BCR-free survival in patients with prostate cancer." (PMID 32466188, 2020).
diabetes (7 papers, 2013 to 2025). "Among other more-expressed proteins in patients with diabetes are CES1, GDF15, and GUSB proteins, which were previously associated to T2D." (PMID 38732002, 2024). "CES1 mRNA in adipose tissue appears to be under strong genetic control and was associated with measures of metabolic function raising the possibility of a potential role of this enzyme in the development of type 2 diabetes mellitus." (PMID 23468884, 2013).
COVID-19 (6 papers, 2021 to 2025). A disease caused by infection with severe acute respiratory syndrome coronavirus 2. "Considering the abundance of CES1 and ubiquity of its inducers and inhibitors in the COVID-19 treatment regimen or in drugs for comorbidities, it is highly likely that remdesivir is affected by non-CYP drugs interactions." (PMID 34358081, 2021). "The optimal 24 feature genes, which were further analyzed by consulting the retrieved literature, we found that four genes (XAF1, OAS2, CES1, RPS8) have been reported in COVID-19." (PMID 35812523, 2022). "While it is well established that COVID-19 can broadly suppress xenobiotic metabolism pathways, the impact of SARS-CoV-2 infection on CES1 and CES2 activity remains underexplored, and experimental validation in hepatocytes or in vivo models needs to be performed." (PMID 40733041, 2025).
Insulin resistance (6 papers, 2012 to 2025). Increased resistance towards insulin, that is, diminished effectiveness of insulin in reducing blood glucose levels. "CES1 mRNA expression level in adipose tissue was positively associated with body-mass index (P<0.001), homeostasis model assessment-insulin resistance (P = 0.003) and level of fasting glucose (P = 0.002), insulin (P = 0.006), and triglycerides (P = 0.003)." (PMID 23468884, 2013). "Although hepatic CES1 deficiency may cause hepatic insulin resistance, skeletal muscle and white adipose tissues are the major organs responsible for plasma glucose clearance." (PMID 25285996, 2014). "If CES1 has a role in the metabolic regulation in the liver that is comparable to its murine ortholog, this would explain our finding that CES1 gene copy number was associated with insulin resistance in the fasting state (HOMA-IR), which is thought to be primarily hepatically determined." (PMID 23468884, 2013). "CES1 gene duplication was positively associated with insulin sensitivity (P = 0.05) as well as glucose tolerance (P = 0.03) and negatively associated with homeostasis model assessment-insulin resistance (P = 0.02)." (PMID 23468884, 2013). "These latter data suggest that hepatic CES1 deficiency may cause hepatic insulin resistance and that the increase in postprandial glucose levels may not be a result of uncontrolled hepatic glucose production." (PMID 25285996, 2014). "However, it has been suggested that the expression of CES1 mRNA in human adipose tissue is correlated with measures of adiposity and metabolic function including waist circumference, homeostasis model assessment-insulin resistance (HOMA-IR), triglyceride level, and plasma insulin level." (PMID 23468884, 2013).
type 2 diabetes (5 papers, 2013 to 2025). "In the present study, we found that Ces1d (CES1 in humans) levels are significantly increased in the type-2 diabetic patients." (PMID 35459739, 2022). "Furthermore, in the adipose tissue of obese and type 2 diabetic patients, the activity of Ces1 is elevated, which is consistent with other studies showing that Ces1 expression is higher in adipose tissue from obese patients compared to lean subjects." (PMID 36978789, 2023).
atrial fibrillation (4 papers, 2022 to 2024). A disorder characterized by an electrocardiographic finding of a supraventricular arrhythmia characterized by the replacement of consistent P waves by rapid oscillations or fibrillatory waves that vary in size, shape and timing and are accompanied by an irregular ventricular response. "We analyzed the genotype–phenotype relationship of ABCB1 (rs1045642, rs4148738, rs2032582, and rs1128503) and CES1 (rs8192935, rs71647871, and rs2244613) polymorphisms in patients with atrial fibrillation who had been treated with dabigatran." (PMID 39011438, 2024). "Our study comprehensively explored the application of dabigatran in atrial fibrillation, cardioembolic stroke, and knee replacement, and other diseases to explore the relationship between CES1 rs2244613 and dabigatran PKs and bleeding risk." (PMID 35990949, 2022). "Another study of patients with atrial fibrillation who received oral dabigatran also concluded that the CES1 SNP rs2244613 was remarkably in association with dabigatran trough concentrations." (PMID 35990949, 2022). "As to treatment for atrial fibrillation, CES1 polymorphism may also affect clopidogrel pharmacological metabolism in the body." (PMID 35990949, 2022). "We evaluated the functional response to dabigatran according to different CES1 and ABCB1 single-nucleotide polymorphisms (SNPs) in patients with atrial fibrillation (AF)." (PMID 38731074, 2024).
bladder cancer (4 papers, 2023 to 2026). "Functionally, CES1 silencing significantly attenuated bladder cancer cell viability, invasive capacity, and migratory potential in vitro." (PMID 41882633, 2026).
Cirrhosis (4 papers, 2014 to 2025). A chronic disorder of the liver in which liver tissue becomes scarred and is partially replaced by regenerative nodules and fibrotic tissue resulting in loss of liver function. "Cirrhosis decreases CES1 expression, leading to significant exposure to oseltamivir and increased risk of toxicity." (PMID 39999160, 2025). "For mild cirrhosis,median abundance was significantly lower than the control for onlyfour proteins: CES1 (by 47%, p = 0.003*), FMO3 (by37%, p < 0.001**), EPHX1 (by 41%, p = 0.005*), MGST3 (by 51%, p = 0.003*), MRP2 (54%, p < 0.001**), and OATP1B1 (by 54%, p < 0.001**)." (PMID 34428046, 2021).
head and neck squamous cell carcinoma (4 papers, 2023 to 2025). A squamous cell carcinoma that arises from any of the following anatomic sites: lip and oral cavity, nasal cavity, paranasal sinuses, pharynx, larynx, and salivary glands. "This activation regulates CES1 expression through the MEK/ERK signaling pathway, thereby contributing to the recurrence and metastasis of head and neck squamous cell carcinoma." (PMID 41196941, 2025).
steatosis (4 papers, 2016 to 2024). Increased lipid within the cytoplasm of cells. "In a protein–protein interaction network, IGSF9 was found to have a central position, being correlated to FGF21, CES1, MAMDC4, and afamin (AFM) in PLHIV with steatosis, and to AFM and GHR in those without steatosis." (PMID 39426127, 2024).
acute myeloid leukemia (3 papers, 2016 to 2025). Acute myeloid leukemia (AML) is a group of neoplasms arising from precursor cells committed to the myeloid cell-line differentiation. "Carboxylesterases (CES), particularly CES1, function as prodrug-activating enzymes, with CES1 expression observed in acute myeloid leukemia (AML) specimens." (PMID 40703077, 2025). "Carboxylesterases (CES) serve as candidate prodrug activating enzymes given CES1 expression in acute myeloid leukemia specimens." (PMID 26496029, 2016).
colorectal tumors (3 papers, 2013 to 2023). "A recent study reported that abnormal TG catabolism by CES1 promotes aggressive colorectal tumor growth." (PMID 36472914, 2023). "The Oncomine database queried to systematically assess relative gene expression levels of PMPMEase (CES1) genes in colorectal tumors." (PMID 23936796, 2013). "This enzyme exhibits a 60-fold higher hydrolytic efficiency against irinotecan than CES1, another human carboxylesterase isozyme, and the ability of colorectal tumors to hydrolyze irinotecan correlates with their expression of CES2, but not CES1." (PMID 29651325, 2018).
melanoma (3 papers, 2019 to 2026). A malignant, usually aggressive tumor composed of atypical, neoplastic melanocytes. "The biological significance of reduced CES1 is less supported by the literature since inhibition of CES1 in vitro and in vivo has been associated with diminished melanoma progression." (PMID 41596411, 2026). "Overall, the identification of CES1 activity in melanoma provides new insights into the metabolic adaptations of these tumors and opens avenues for exploring diagnostic or therapeutic opportunities for melanoma characterization and treatment." (PMID 39934865, 2025). "This suggests that CES1, particularly the Ces1c isoform, is the dominant enzyme responsible for 2-AG degradation in melanoma of the BRafV600E/Pten−/− mouse model." (PMID 39934865, 2025). "Given the elevated levels of SAG, 2-AG, and ARA observed in mouse melanomas, along with the detection of active Ces1 isoforms in both melanoma and skin tissues, we next evaluated the effects of in vivo Ces1 inhibition on melanoma progression." (PMID 39934865, 2025). "This study not only sheds light on the metabolic flexibility of melanomas but also suggests the exploration of targeted therapeutic interventions involving CES1 inhibition." (PMID 39934865, 2025). "Using chemoproteomics, we show the expression of multiple Ces1 isoforms—Ces1c, Ces1d, and Ces1f—in mouse melanoma and normal mouse and human (Ces1) skin." (PMID 39934865, 2025). "To confirm the efficacy of the in vivo Ces1 inhibition, we conducted ex vivo ABPP on both melanoma and skin samples, showing that Ces1 was effectively inhibited in the JZL184-treated group, indicated by a clear reduction in the ex vivo ABPP." (PMID 39934865, 2025). "CES1 inhibition in the tumor tissues led to a marked slowdown in melanoma growth, suggesting a role of 2-AG and potentially local ARA metabolism that cannot be easily detected in the tumor tissue, independent of prostaglandins." (PMID 39934865, 2025). "This study is the first to demonstrate that metabolic pathways involving elevated levels of SAG, 2-AG, and ARA may contribute to melanoma progression, with CES1 directly influencing lipid metabolism within the melanoma tumor microenvironment." (PMID 39934865, 2025). "Importantly, our in vivo experiments revealed that in tumors with elevated SAG levels, inhibiting Ces1c markedly impairs melanoma tumor growth, highlighting CES1 as a potential therapeutic target for malignant melanoma." (PMID 39934865, 2025). "CES1 expression could thus be a potential marker for classifying these aggressive melanoma subtypes." (PMID 39934865, 2025). "CES1 expression and high SAG, 2-AG, and ARA levels may be a signature of specific BRAF-driven malignant melanoma subtypes which are associated with discrete metabolic adaptations." (PMID 39934865, 2025). "Following up on our findings regarding the role of CES1/Ces1 in 2-AG/2-OG hydrolysis and melanoma progression, we analyzed the available RNA sequencing (RNA-seq) data on the expression of 2-AG-hydrolysing enzymes in both human malignant melanoma and human skin tissues." (PMID 39934865, 2025). "Additionally, scRNA-seq data from previous studies revealed divergent MAGL/CES1 expression patterns across different human melanoma subtypes." (PMID 39934865, 2025). "Future studies will have to explore the long-term effects of CES1 inhibition and the mechanism of action of 2-AG and other lipids, their roles in metastasis, and their impact on overall survival in melanoma, potentially paving the way for novel therapeutic approaches in melanoma treatment." (PMID 39934865, 2025). "Methylation inactivation of tumor suppressor SPINT2 was diagnosed with the growth of melanoma, but the inactivation of this gene may be associated with the development of EOC.CES1, HIST1H1C andSPINK6 were novel biomarkers for pathogenesis of EOC in these GO terms." (PMID 30970615, 2019).